AFP (alpha fetoprotein)
Diseases named in the same sentence as AFP in open-access papers (continued):
Sharing a sentence is not in itself a finding about the gene and the disease.
hepatocellular carcinoma (continued). "For some cancers, promoters that regulate the expression of tumor-specific antigens (TSAs) are optimal candidates for OVTs; for example, the alpha-fetoprotein (AFP) promoter for hepatocellular carcinoma and the prostate-specific antigen (PSA) promoter for prostate cancer." (PMID 36505792, 2022). "It suggests that AFP-L3 could be used to exclude hepatocellular carcinoma in the presence of elevated AFP." (PMID 36072925, 2022). "The median survival rate of hepatocellular carcinoma patients with high serum AFP level is low." (PMID 35144566, 2022). "More than two imaging techniques discover a space-occupying liver lesion and that the serum alpha-fetoprotein (AFP) level is extremely elevated, which means that hepatocellular carcinoma (HCC) could be diagnosed." (PMID 36457572, 2022). "However, patients with hepatocellular carcinoma usually have a history of liver disease such as hepatitis B and cirrhosis, and AFP level is usually elevated." (PMID 35928867, 2022). "AFPGC refers to the serum and gastric cancer tissue containing a large amount of AFP with the exclusion of other possible diseases (hepatocellular carcinoma, active liver disease, genitourinary system tumors) that may produce AFP." (PMID 35886934, 2022). "Alpha-fetoprotein acts as the most common tumor marker used for hepatocellular carcinoma diagnosis." (PMID 34680245, 2021). "Currently, glycosylated proteins have become one of the most common cancer biomarkers in the clinic, such as alpha-fetoprotein (AFP) for hepatocellular carcinoma, carcinoembryonic antigen (CEA) for colon cancer and prostate specific antigen (PSA) for prostate cancer." (PMID 33931075, 2021). "In first clinical trials, vaccinations against tumor-associated antigens (TAA), such as Alpha-Fetoprotein (AFP) using dendritic cells (DC) failed to achieve effective immune responses towards hepatocellular carcinoma (HCC)." (PMID 34282787, 2021). "In addition, HBx, a HBV regulatory protein that promotes the development of HBV-associated hepatoma, can interact with HBP1, inhibiting the binding of HBP1 to the AFP promoter region and leading to up-regulated AFP expression." (PMID 33794968, 2021). "AFP is a major plasma protein and serves as a biomarker for hepatocellular carcinoma." (PMID 34201882, 2021). "It has also been shown that the combination of serum miR‐27a and miR‐125b, in conjugation with α‐fetoprotein (AFP), can be used to enhance the specificity and sensitivity of AFP‐negative HBV‐associated early‐stage hepatocellular carcinoma diagnosis." (PMID 33332677, 2021). "Moreover, we observed that 82.3 cells expressed α-fetoprotein (AFP), a marker of hepatocellular carcinoma, sometimes detected in BTC." (PMID 33922695, 2021). "Furthermore, AFP inhibits autophagy to promote malignant behavior in hepatocellular carcinoma cells by activating PI3K/AKT/mTOR signaling." (PMID 33966049, 2021). "Alpha-fetoprotein (AFP), a glycoprotein, is the most commonly used serum marker for the diagnosis of hepatoma in clinical practice and is widely used in screening, diagnosis, efficacy evaluation and recurrence assessment of hepatoma." (PMID 33794968, 2021). "Although AFP increases in liver cancers, elevated AFP levels may accompany acute hepatic flare attacks and this may lead to suspected hepatocellular cancer." (PMID 34194888, 2021). "Furthermore, we included transaminases (ALAT, ASAT), alkaline phosphatase (AP), and γ-glutamyltransferase (GGT) as diagnostic biomarkers for injury of hepatocytes and alpha-fetoprotein (AFP) as a tumor marker for hepatocellular carcinoma." (PMID 34492024, 2021). "A number of blood-based protein biomarkers have been used for human cancer screening and monitoring using immunohistochemical methods, including: CEA for colorectal cancer, PSA for prostate cancer, CA-125 for ovarian cancer, and alpha-fetoprotein (AFP) for hepatocellular carcinoma." (PMID 33834049, 2021).
hepatocellular carcinoma (continued). "PRMT5 is overexpressed in hepatocellular carcinoma (HCC), and associated with aggressive clinicopathological parameters, such as poor differentiation, higher incidence of hepatic vein invasion, larger tumor size, higher AFP levels and worse prognosis." (PMID 34513846, 2021). "The deregulation of AFP by HBP1 contributed to hepatoma progression in mice." (PMID 33794968, 2021). "The inverse relationship of HBP1 and AFP in hepatoma patients correlates with hepatoma relapse." (PMID 33794968, 2021). "Currently, glycoproteins are the most used cancer biomarkers in the clinic, such as alpha-fetoprotein (AFP) for hepatocellular carcinoma, cancer antigen 125 (CA125) for ovarian cancer, carcinoembryonic antigen (CEA) for colon cancer, and prostate specific antigen (PSA) for prostate cancer." (PMID 32583064, 2021). "Our data clarify the mechanism of HBP1 in inhibiting the expression of AFP and its suppression in malignancy of hepatoma cells, providing a more comprehensive theoretical basis and potential solutions for the diagnosis and treatment of hepatoma." (PMID 33794968, 2021). "Thus, a combination of albumin-bilirubin grade and alpha-fetoprotein level can be used to stratify patients with unresectable hepatocellular carcinoma by progression-free survival and overall survival probability for sorafenib–regorafenib sequential therapy." (PMID 34359658, 2021). "The repression of AFP by HBP1 inhibited the malignancy of hepatoma cells." (PMID 33794968, 2021). "Furthermore, we identified that 82.3 cells expressed AFP, a key biomarker of hepatocellular carcinoma." (PMID 33922695, 2021). "In first clinical trials, vaccinations against tumor-associated antigens (TAA), such as Alpha-Fetoprotein (AFP) using antigen presenting cells, such as dendritic cells (DC), failed to achieve effective immune responses towards hepatocellular carcinoma (HCC)." (PMID 34282787, 2021). "A high level of the serum AFP level is highly suspicious of hepatocellular carcinoma." (PMID 33490235, 2020). "AFP (alpha-fetoprotein), a biomarker of hepatocellular carcinoma, is the target gene of miR-1270." (PMID 33335899, 2020). "Positive AFP proved that both cells were hepatocellular carcinoma cells." (PMID 32433581, 2020). "Elevated expression of AFP has been found in radiation-induced hepatocellular carcinomas." (PMID 33382739, 2020). "Alpha-fetoprotein (AFP) was normal, and biopsy showed hepatocellular carcinoma." (PMID 32983688, 2020). "Based on the results, we propose that reduced TUG1 function is an important contributor to regulation of AFP expression in hepatoma cell lines and T3/TR, TUG1 and AFP may serve as potential prognostic biomarkers for NBNC-HCC." (PMID 31973032, 2020). "The AFP gene is expressed during embryonic development by the liver and yolk sac and is down-regulated soon after the birth to be re-expressed in adult patients with hepatocellular carcinoma (HCC)." (PMID 32019136, 2020). "Therefore, despite the highly specific and pronounced expression of AFP in hepatocellular carcinoma cells, the immunologic reaction to AFP is insufficient as an acquired immune tolerance has developed." (PMID 32784389, 2020). "In addition, the AUC of AFP was 0.765, so they came to the conclusion that AFP was a useful single biomarker for diagnosing hepatocellular carcinoma." (PMID 31218849, 2020). "AFP is not only a marker of hepatocellular carcinoma, but also a biomarker of liver regeneration." (PMID 32293297, 2020). "AFP is used as a tumor biomarker for the diagnosis and follow-up of hepatocellular carcinoma." (PMID 31568519, 2019). "A previous study reported that minimum absolute lymphocyte count (min ALC), Barcelona Clinic Liver Cancer (BCLC) score, and serum alpha-fetoprotein (AFP) are independent prognostic factors for the survival of patients with hepatocellular carcinoma (HCC) treated with RT." (PMID 31781521, 2019).
hepatocellular carcinoma (continued). "Alpha-fetoprotein (AFP), one of the specific tumor markers for hepatocellular carcinoma, was below the normal level in most patients with ICC (n = 78, 73.6%), while CA19–9 was above the cut-off value in majority of patients (n = 73, 68.9%) included in the study." (PMID 30849953, 2019). "Hepatocellular carcinoma can be detected from elevated alpha-fetoprotein (AFP) levels." (PMID 31426613, 2019). "AFP is one of the most common biomarkers for hepatocellular carcinoma (HCC)." (PMID 30151798, 2019). "While many hepatocellular carcinoma tumors express AFP and PIVKA-II at levels which may be detectable in the serum, preoperative AFP and PIVKA-II are not usually measured in patients with pancreatic HC." (PMID 31784920, 2019). "Researches indicated that blocking AFP could inhibit the proliferation of hepatoma cells and induce apoptosis of cancer cells." (PMID 29805966, 2018). "This may indicate that the value of LDH is superior to that of AFP in predicting overall survival in patients with hepatocellular carcinoma, whereas AFP is superior to LDH in predicting recurrence-free survival in patients with hepatocellular carcinoma." (PMID 30687735, 2018). "In this study, was also observed that higher liver stiffness get by TE and ARFI methods associated with increased values ​​of serum AFP and etiology of hepatitis C virus (HCV) were positive predictors to the presence of hepatocellular carcinoma (HCC) in patients with liver cirrhosis." (PMID 29947694, 2018). "For patients receiving radiotherapy for recurrence of hepatocellular carcinoma, a 75% decline in AFP levels at 3 months may be a predictor of survival prognosis." (PMID 29687004, 2018). "However, despite exposure to high plasma levels of AFP during hepatocellular carcinoma development, only low immunity is mounted against the protein." (PMID 29805966, 2018). "AFP may protect hepatoma cells from immune surveillance by enhancing lymphocyte apoptosis and inhibiting hepatoma cell apoptosis." (PMID 29696820, 2018). "However, we presented two independent risk factors for hepatocellular carcinoma like the HCV etiology and increased serum levels of AFP were demonstrated." (PMID 29947694, 2018). "A high serum AFP level is used as diagnostic criteria for hepatocellular carcinoma (in the absence of a testicular tumor)." (PMID 30112355, 2018). "AFP is also secreted in other tumors such as hepatocellular carcinoma and testicular carcinoma." (PMID 29933751, 2018). "In conclusion, we have identified that the significance in the prediction of primary hepatocellular carcinoma could be improved by adjusting the serum AFP levels with genetic effects." (PMID 29696820, 2018). "In patients with hepatocellular carcinoma, TYRO3 expression was significantly associated with higher levels of serum and intratumoral alpha-fetoprotein, which is an independent diagnostic predictor of disease stage, disease progression, and poorer overall survival." (PMID 30501104, 2018). "Our previous study revealed that FGFR4 rs351855 might be related with the risk of hepatocellular carcinoma (HCC) associated with liver cirrhosis and might increase the alpha-fetoprotein level in Taiwanese patients with HCC." (PMID 29221201, 2017). "AFP also correlates closely with the growth rate (number of dividing cells) and size of the tumour as well as progressive elevation of alpha fetoprotein in biopsied liver samples of patients with liver cirrhosis and hepatocellular carcinoma." (PMID 29268718, 2017). "Alpha-fetoprotein (AFP) is a biomarker for hepatocellular carcinoma (HCC)." (PMID 29207969, 2017). "Also, an elevated AFP concentration in the serum of adults was primarily observed in patients with hepatocellular carcinoma, chronic hepatitis, and acute liver failure." (PMID 29206210, 2017).
hepatocellular carcinoma (continued). "Further research with optimized designs, greater numbers of studies, and larger sample sizes are required to shed light on remaining inconsistencies in variant results of combining des-gamma-carboxyprothrombin and alpha-fetoprotein for hepatocellular carcinoma diagnosing." (PMID 29163838, 2017). "Combination of the University of California, San Francisco (UCSF) and the up-to-7 criteria with alpha-fetoprotein (AFP) cutoff of 100 ng/ml was proposed as the Warsaw expansion of the Milan criteria in selection of hepatocellular cancer (HCC) patients for liver transplantation." (PMID 27531306, 2017). "There is paucity of information concerning whether AFP change is a predictor of prognosis for recurrent hepatocellular carcinoma (RHCC) patients after trans-arterial chemoembolization (TACE)." (PMID 29156744, 2017). "Additionally, serum levels were measured for AFP, a screening substance for a subset of abnormalities such as hepatocellular carcinoma and calcitonin, which is produced in humans and rodents primarily by the parafollicular cells in the thyroid." (PMID 28422070, 2017). "Our novel aAPC system could provide a robust platform for the generation of functional AFP-specific CTLs for adoptive immunotherapy of hepatocellular carcinoma." (PMID 27007051, 2016). "AFP itself is an oncofetal protein and was first found to be a marker of hepatoma." (PMID 27136596, 2016). "It was reported that soluble AXL could outperform AFP in diagnosing very early hepatocellular carcinoma and correlated with tumor stage as well as patient survival in renal cell carcinoma." (PMID 27015365, 2016). "AFP is an oncofetal protein found in hepatocellular cancer, cirrhosis, and hepatitis." (PMID 26777057, 2016). "In addition, we also analyzed the correlation between the percentages of PD-L1+MDSCs and Child-Pugh grade and serum concentration of well-known hepatocellular cancer biomarkers (AFP, AFP-L3 and PIVKA II)." (PMID 27966626, 2016). "Serum AFP is a routinely used marker for hepatocellular carcinoma." (PMID 26640716, 2015). "Reduced AFP in the AFP-siRNA transfected, ChIP results indicated that human hepatoma PLC/PRF/5 cells were transfected with AFP-siRNA vectors led to an apparent reduction of binding of p-mTOR(Ser2448) to the promoter elements in the 5′-flanking region of the CXCR4 gene compared to the input." (PMID 25815363, 2015). "The expression of AFP/AFPR are correlated with hepatocellular carcinoma(HCC)-initial cells." (PMID 25943101, 2015). "The aim of this study therefore, was to determine the relative sensitivity and specificity of des-gamma-carboxyprothrombin and alpha-fetoprotein in the diagnosis of hepatocellular carcinoma in a cohort of Nigerian patients presenting at a single referral centre." (PMID 26341083, 2015). "AFP is often measured as a tumor marker for diagnosing hepatocellular carcinoma (HCC)." (PMID 27275221, 2015). "We have recently provided some evidence to illustrate that cytoplasmic AFP may function in the upregulation of PI3K/AFT pathways in human hepatocellular carcinoma cells through binding to PTEN (phosphatase and tensin homolog)." (PMID 26078940, 2015). "However, the consecutive increase of AFP level in a patient with liver cirrhosis should always raise the suspicion of hepatocellular carcinoma." (PMID 25922775, 2015). "In addition, patients with advanced-stage hepatocellular carcinomas had significantly higher median AFP serum levels (BCLC B/C) than that of early-stage tumors (BCLC 0/A) (300 ng/mL versus 17 ng/mL, P = 0.0014)." (PMID 25737783, 2015). "Furthermore, groundbreaking biomarkers for hepatocellular carcinoma are being discovered, although alpha-fetoprotein remains one of the most frequently used serum test in the early stages." (PMID 25866565, 2015).
hepatocellular carcinoma (continued). "The question was brought up again in 1963 after the discovery by electrophoretic and or immunodiffusion techniques of an aldolase A of foetal type in soluble extracts of rat hepatomas and of a protein (alpha-fetoprotein) in the sera of adult mice bearing chemically induced hepatomas." (PMID 26346166, 2015). "Alpha fetoprotein (AFP) is a clinical biomarker of hepatocellular carcinoma (HCC)." (PMID 25714026, 2015). "On the other hand, hepatocellular carcinoma often shows high expression of AFP." (PMID 25105025, 2014). "Furthermore, our findings support the theory of a consistent collapse in the Hippo axis, as well as an expression of the stemness factor NANOG in high alpha-fetoprotein-expressing hepatocellular carcinomas." (PMID 25502816, 2014). "Hepatoma cells can synthesize various tumor-related proteins, such as AFP." (PMID 24416255, 2014). "In this study, we replaced them with tissue specific promoters: i) the alpha fetoprotein (AFP) promoter drives expression of AFP in the embryonic liver and in hepatocellular carcinomas, ii) the SM22 promoter has been described as tissue-specific promoter for smooth muscle cells." (PMID 23734827, 2013). "With the AFP promoter-driven pEPito vector hepatocellular carcinoma-specific expression could be achieved in vivo after systemic vector application together with polyethylenimine as transfection enhancer." (PMID 23734827, 2013). "The third, most rarely used, and most difficult type of approach to develop allows for detection and quantification of both total protein levels and associated glycan structure(s), such as the measurement of the core-fucosylated species of AFP in hepatocellular carcinoma." (PMID 23390961, 2013). "Studies of AFP knockdown by siRNA found inhibited cell proliferation in hepatomas." (PMID 23382965, 2013). "The other cells were derived from differentiated hepatomas and produced AFP." (PMID 23064776, 2013). "MACC1 expression is significantly related to vascular invasion and alpha-fetoprotein level, which might serve as a novel prognostic marker in hepatocellular carcinoma." (PMID 24325214, 2013). "However, overall it seems highly likely that a substantial proportion of the reported FLC cases with elevated serum AFP are misdiagnosed and should have been classified as typical hepatocellular carcinoma." (PMID 24278737, 2012). "The primary malignancies associated with AFP elevations are hepatocellular carcinoma and nonseminomatous germ cell tumors." (PMID 27785191, 2012). "As well as being produced by the tumor, AFP may play a role in tumor growth, as preclinical evidence has shown that AFP may have a modulatory effect on hepatoma cells." (PMID 22559879, 2012). "Furthermore, the high expression of CD133 is correlated with the increased tumor grade, advanced disease stage, elevated serum alpha-fetoprotein levels and poor survival of the patients with hepatocellular carcinoma." (PMID 21798073, 2011). "Additionally, elevated levels of serum AFP have been reported to occur with several tumor types other than hepatocellular carcinoma and embryonic cell carcinoma." (PMID 22018031, 2011). "However, the tumor in our patient also differed from hepatocellular carcinoma in terms of the histological and morphological features, which eventually led to the final diagnosis of AFP-producing lung adenocarcinoma." (PMID 21554678, 2011). "Alpha-fetoprotein (AFP) is a well-known tumor marker related to hepatocellular carcinoma (HCC)." (PMID 22164043, 2011). "In the induction of a T-cell mediated immune response, two juxtaposed sequences on GIP-34 were demonstrated to serve as epitopes for antigen presentation of dendritic cells to T-cells to induce cytotoxic lymphocytes directed against AFP bound to hepatoma cells." (PMID 24212829, 2011). "AFP-producing tumors, others than hepatocellular carcinoma, have been described." (PMID 19674468, 2009).